INS (insulin)
Diseases named in the same sentence as INS in open-access papers (continued):
Sharing a sentence is not in itself a finding about the gene and the disease.
type 2 diabetes (continued). "After MK-7 intervention, we observed notable 13.4%, 28.3%, and 7.4% reductions in fasting serum glucose (P = 0.048), insulin (P = 0.005), and HbA1c levels (P = 0.019) in type 2 diabetes participants and significant glucose tolerance improvement in diet-induced obesity mice (P = 0.005)." (PMID 37147641, 2023). "That GPER also functions to enhance insulin secretion in humans has been demonstrated in pancreatic islets isolated from type 2 diabetic patients where glucose-stimulated insulin secretion increased, while glucagon and somatostatin secretion decreased, upon G-1 stimulation." (PMID 36662583, 2023). "In this observational cohort study, we used the Maccabi Healthcare Services (MHS) database, Israel's second-largest healthcare maintenance organization (HMO), to compare kidney outcomes in patients with type 2 diabetes initiating GLP-1 RAs versus basal insulin." (PMID 37244998, 2023). "This study evaluated the efficacy of GLP-1 RAs in patients with type 2 diabetes on insulin and patient factors that may predict a beneficial clinical response." (PMID 37589043, 2023). "In type 2 diabetes, the function of incretins is reduced, and insulin secretion is impaired." (PMID 38139019, 2023). "Indeed, it has been suggested that glucagon elevation occurs in prediabetes and type 2 diabetes to stimulate insulin secretion by the β cell." (PMID 37751301, 2023). "However, to the best of our knowledge, no studies have yet been done to examine feeding/fasting-dependent regulation of the proinsulin pool size in the islets of insulin-resistant type 2 diabetic patients or animal models." (PMID 37209827, 2023). "Its stabilization by controlling DPP-IV activity promotes insulin secretion, leading to decreased blood glucose levels and thereby affecting the control of glycemia (an indicator of blood glucose levels) in patients with type 2 diabetes." (PMID 38202792, 2023). "Human diseases and organismal system-related PPI comprised 26 nodes and 92 edges, and DEPs were enriched in pancreatic secretion, maturity-onset diabetes of the young, type I diabetes mellitus, type II diabetes mellitus, insulin signaling pathway, insulin resistance, and pancreatic cancer." (PMID 40303782, 2023). "Studies in rodents have shown that changes in the gut microbiome, such as an increase in the genus Firmicutes, correlate with changes in the regulation of insulin levels, such as the presence or progression of obesity, type 2 diabetes, and the metabolic syndrome." (PMID 38136074, 2023). "Ile-Pro, Met-Pro, Val-Pro, and Leu-Pro are dipeptides with direct inhibitory activity against dipeptidylpeptidase-IV, which metabolizes the insulin-tropic hormone glucagon-like peptide-1, used to control postprandial hyperglycemia in type 2 diabetes, and to prevent and treat type 2 diabetes." (PMID 36358531, 2022). "Although the benefit for CGM is largely accepted in patients with type 2 diabetes on intensive insulin treatment, there is increasing evidence that it may play a role in T2D that is not treated with prandial insulin." (PMID 35631264, 2022). "A more important fact is that L-arginine may have the potential to prevent and/or relieve type 2 diabetes by restoring insulin sensitivity." (PMID 36613966, 2022). "The decreased function of the CD38 mutant may have contributed to the impairment of glucose-stimulated insulin secretion in type 2 diabetes patients." (PMID 35457121, 2022). "Partial mediation was observed for two traits: fasting insulin, which is difficult to separate from the clinical definition of type 2 diabetes, and hip circumference, though this particular trait was only an exception for the outcome liability to coronary artery disease." (PMID 35129650, 2022). "The pathophysiology of type 2 diabetes involves insulin and glucagon." (PMID 35409362, 2022). "However, the eventual failure of β-cells to compensate follows, resulting in insufficient levels of insulin and the development of type 2 diabetes." (PMID 35563231, 2022).
type 2 diabetes (continued). "However, no treatment studies have reported effects on BW in animal models of type 2 diabetes or with treatments other than insulin in those of type 1 diabetes." (PMID 36003651, 2022). "A similar study of the PaQ (a wearable device) was carried out to determine basal rates and bolus insulin on demand; adults with type 2 diabetes showed improved glycemic control using a PaQ device and were satisfied with the change from daily injections (NCT02419859)." (PMID 35890301, 2022). "Pancreatic insulin production is elevated in type 2 diabetes and obesity." (PMID 36244663, 2022). "The pooled prevalence of EPI was 27% (95% CI: 17%–37%, I2 = 90.95%) in type 2 diabetes patients with higher insulin requirement group (1 group), while patients with lower insulin requirement group (2 group) had a lower incidence of EPI (15%, 95% CI: 1%–40%, I2 = 95.17%)." (PMID 36213198, 2022). "Finally, expression of pathways involved with insulin signaling and type II diabetes mellitus were increased with rapamycin treatment, further confirming the important role of mTOR in regulating glucose metabolism and insulin sensitivity." (PMID 35316218, 2022). "Using the HFD + higher STZ dose, we report the induction of hyperglycaemia, impaired glucose tolerance, hyperlipidaemia and continued decline in beta cell insulin‐production, which are hallmarks of established type 2 diabetes where patients are typically diagnosed." (PMID 35128667, 2022). "The increased prevalence of insulin-related somatic diseases (i.e., type 2 diabetes mellitus (T2DM), obesity, and metabolic syndrome (MetS)) observed in mental disorders, with a resulting increased cardiovascular risk, contributes significantly to the lower life expectancy." (PMID 35165256, 2022). "Pancreatic samples were not available for our PD cases, but mercury can be taken up by human pancreatic insulin-producing beta cells, so mercury exposure could contribute to the increased incidence of type 2 diabetes in PD." (PMID 35015796, 2022). "The presence of sustained insulin secretion and thus, C-peptide 3-5 years after diagnosis may indicate type 2 diabetes." (PMID 35784568, 2022). "In addition, insulin treatment is also needed in older patients with type 2 diabetes, who fail to achieve glycemic target after lifestyle intervention and non-insulin therapy." (PMID 36249753, 2022). "Multivariate regression analysis of the data collected from the Insulin Resistance Atherosclerosis Study (IRAS) showed a strong association of palmitic acid with Type-2 diabetes risk independent of insulin sensitivity." (PMID 36078086, 2022). "In addition, Camta1 has been proved to regulate miR-132 to modulate insulin production and secretion in the pathology of the type 2 diabetes rat model." (PMID 35800215, 2022). "These dissimilarities could be due to the inclusion in the study by of only obese children, and some of them with type 2 diabetes on insulin or metformin treatment which might interfere with triglyceride, glucose, and insulin metabolism." (PMID 35586828, 2022). "In our cohort, insulin use was associated with a 20% excess for all sites cancer incidence among people with type 2 diabetes, while this excess was not appreciable in people with type 1 diabetes." (PMID 35681699, 2022). "We therefore firstly determined whether type 2 diabetes was associated with changes in serum ADAM10 levels and examined the effect of exogenous insulin therapy on ADAM10 levels." (PMID 35705192, 2022). "However, these strategies are inadequate in curing the insulin insensitivity seen in obesity and type 2 diabetes or preventing disease progression." (PMID 36143977, 2022). "Tissue-specific inhibition of pyruvate carboxylase reduced plasma glucose concentrations and could be a potential therapeutic approach for nonalcoholic fatty liver disease, hepatic insulin resistance, and type 2 diabetes." (PMID 35799202, 2022).
type 2 diabetes (continued). "Importantly, in patients with advanced type 2 diabetes, these medications fail to effectively regulate hyperglycemia, and these patients have to be placed on insulin replacement therapy." (PMID 35327570, 2022). "Insulin can be used to treat type I diabetes, whereas medications that inhibit specific enzymes, such as α-amylase, α-glucosidase, dipeptidyl peptidase IV, and protein tyrosine phosphatase, can be used to treat type II diabetes." (PMID 35308202, 2022). "Demographic factors contributing to an increased risk of IUFD in our cohort were maternal obesity (p = 0.002), smoking (p<0.001), chronic hypertension (p = 0.015), antiphospholipid syndrome (p = 0.017), type 2 diabetes (p<0.001), and insulin requirement (p<0.001)." (PMID 35051188, 2022). "We hypothesised that repeated oscillations in hepatic and intramuscular energy stores induced by ADF per se, would increase the β-cell secretory capacity and insulin sensitivity and improve glucose homeostasis in patients with type 2 diabetes." (PMID 36531168, 2022). "Regular insulin injections are the mainstay of care for people with type 2 diabetes." (PMID 36187456, 2022). "In the long term the digital system could improve quality and safety for basal insulin therapy in persons with type 2 diabetes at home." (PMID 36992745, 2022). "Human insulin was used as a model amyloidogenic protein for studying protein kinetics with applications to in situ pharmaceutical production, tissue engineering, and diseases such as Alzheimer’s, Parkinson’s, infectious prions, and type 2 diabetes." (PMID 36127358, 2022). "This study aims to investigate the effect of the glucagon-like peptide-1 (GLP-1) receptor agonist (GLP-1RA) liraglutide on retinal pathological findings as compared with insulin and hydralazine using an animal model of type 2 diabetes with obesity, hypertension, and hyperlipidemia." (PMID 35524186, 2022). "Moreover, metformin, an insulin-sensitizer used as the first-line drug for treating type 2 diabetes, does not only lower plasma insulin and glucose levels, but also can reduce ACTH levels and cortisol." (PMID 35897752, 2022). "Therefore, some drug therapies with antidiabetic effects such as insulin and synthetic medication are used to treat type 2 diabetes." (PMID 35564076, 2022). "In conclusion, both diets may reduce type 2 diabetes risk albeit, a LCHF diet may enhance insulin sensitivity by increasing lipid oxidation." (PMID 36145067, 2022). "Moreover, type 2 diabetes is characterized by decreased IR expression in WAT, demonstrating that reduced insulin sensitivity with decreased IR expression is tightly linked to adipocyte dysfunction." (PMID 35624726, 2022). "Type 2 diabetes (T2D), which accounts for >90% of diabetic patients, is a heterogeneous group of disorders that share a common feature of chronic hyperglycemia resulting from defects of insulin secretion, insulin action, or both." (PMID 35682864, 2022). "It is possible that patients with type 2 diabetes have lower engagement in healthy lifestyle changes, which reflects on their motivation to understand the nutritional value of food and apply their competencies during insulin management." (PMID 36078271, 2022). "Studies have shown that type 2 diabetes is characterized by chronic hyperglycemia due to a reduction in insulin response, inflammation, metabolic dysregulation, increased formation of free radicals, and decreased antioxidant capacity, eventually causing disease complications." (PMID 36531176, 2022). "As l-Ser supplementation is suggested to enhance insulin secretion, our observed increase in l-Ser levels may be the result of diseased islets countering the changes in insulin secretion during type 2 diabetes development." (PMID 36144204, 2022). "Sulfonylureas are used clinically to promote insulin secretion in type 2 diabetes." (PMID 35954249, 2022).
type 2 diabetes (continued). "The authors observed that pearl millet evoked insulin separation in healthy persons, which decreased the gastrointestinal tract, whereas the insulin reserve in type 2 diabetics could have been inadequate to mobilize insulin after ingestion of pearl millet." (PMID 35889889, 2022). "The main reasons for the development of type 2 diabetes can be categorized into two points: inadequate ability of insulin-sensitive tissues to respond to insulin and a defect in the ability of pancreatic beta cells to secrete insulin." (PMID 36230037, 2022). "We found no indices of increased incident type 2 diabetes risk, except for a blunted first-phase insulin response compared with age- and BMI-matched controls that did not exceed the reference range." (PMID 36557270, 2022). "It is a chronic disease characterized by hyperglycemia caused by a lack of insulin secretion from the pancreatic β cells (in type 1 diabetes—T1DM) or insulin resistance (in type 2 diabetes—T2DM)." (PMID 35743147, 2022). "In addition, insulin activity in a type II diabetes mouse model was restored upon oral administration of Eubacterium hallii." (PMID 36687672, 2022). "The mTOR pathway is activated during various cellular processes and its function has been implicated in multiple diseases, including tumor formation, angiogenesis, insulin resistance, adipogenesis, and is deregulated in pathological conditions (e.g., cancer and type 2 diabetes)." (PMID 36470863, 2022). "This process may resemble the central and peripheral insulin resistance that occurs in brain neurodegenerative conditions and in type 2 diabetes." (PMID 35444190, 2022). "In human type 2 diabetes, adipose tissue plays an important role in disturbing glucose homeostasis by secreting factors that affect the function of cells and tissues throughout the body, including insulin-producing pancreatic beta cells." (PMID 35326375, 2022). "Dietary fiber can also prevent type 2 diabetes by improving insulin sensitivity in the body." (PMID 35702290, 2022). "In this manuscript, we offer the hypothesis that it is an insulin secretion defect that drives the IR responsible for the pathophysiology of type 2 diabetes." (PMID 35163806, 2022). "Though many randomized control trials had examined the effectiveness and safety of taking insulin therapy with or without metformin, there are limited real-world data, especially among Chinese type 2 diabetes patients initiating basal insulin (BI) with uncontrolled hyperglycemia by oral agents." (PMID 35045841, 2022). "Type 2 diabetes is described as an inadequate amount of insulin sensitivity over time." (PMID 36060389, 2022). "In patients with insulin-treated type 1 and type 2 diabetes the use of the GlucoonlineTM system resulted in a 0.38% decrease in HbA1c from baseline and a higher proportion of patients achieving a HbA1c target level of less than 7%, as compared with standard of care." (PMID 35476320, 2022). "A reduced PGC-1α expression could be observed in the skeletal muscle of patients with type 2 diabetes and in the adipose tissue of insulin-resistant and pathologically obese people." (PMID 35622482, 2022). "In type 2 diabetic patients, RN has been shown to offer a variety of effects, including lowering blood glucose and glycosylated haemoglobin levels, promoting insulin release, and decreasing glucagon synthesis, therefore improving pre- and postprandial blood glucose." (PMID 36233271, 2022). "Indeed, impaired insulin signalling has been shown to hinder the uptake of glucose in T cells, thus providing a potential mechanism for such defects in type 2 diabetes." (PMID 36304475, 2022). "In addition, a study in Malaysia found that insulin and metformin were the most frequently used medications for type 2 diabetes." (PMID 35742447, 2022). "Insulin supplementation during the early stage of type 2 diabetes was an effective therapy." (PMID 35308210, 2022).
type 2 diabetes (continued). "This is because the DEPS-R has different psychometric properties according to whether the person under examination has type 1 diabetes requiring insulin, versus type 2 diabetes." (PMID 35978344, 2022). "Preceding hyperinsulinemia and high therapeutic insulin concentrations could explain the prevalence of gastric cancer in type II diabetics." (PMID 34554347, 2022). "The other detrimental effect of the release of IL-17 in adipose tissue is long-term reduced insulin sensitivity, which could be responsible for the development of diabetes mellitus type II as a part of metabolic syndrome." (PMID 35277002, 2022). "Several studies have suggested that legume consumption improves multiple cardiovascular risk factors (blood pressure, LDL concentrations in blood, body weight) and protects against type 2 diabetes, reducing glycated hemoglobin levels in diabetic patients and improving insulin sensitivity." (PMID 34671828, 2022). "Thus, our studies suggest that the decline in spliced XBP1 expression found in type 2 diabetes contributes to the failure of beta cells to secrete sufficient amounts of insulin to meet metabolic demand." (PMID 35316840, 2022). "Therefore, in long-term prospective cohort studies, decreased β-cell function is initially observed in Asians, whereas decreased insulin sensitivity is initially observed in Caucasians when switching from normoglycemia to type 2 diabetes." (PMID 35057420, 2022). "Prior studies have shown an impaired insulin-stimulated myocardial glucose metabolism in patients with type 2 diabetes with or without CHD and in subjects at increased risk of T2DM." (PMID 35845046, 2022). "Several findings in our study indicate that the high prevalence of EPI in type 2 diabetes patients may be closely related to beta cell function, which determines plasma insulin levels." (PMID 36213198, 2022). "Overdoses of insulin can result in hypoglycemia that may lead to behavioral and cognitive disturbance, coma, brain damage, and even death." (PMID 35200456, 2022). "Insulin treatment, especially basal-bolus treatment, is fundamental to the medication of teenagers and children having type-I diabetes just as with adults and is a pivotal molecule in the therapy of type-II diabetes." (PMID 35723344, 2022). "High therapeutic insulin doses are required to overcome insulin resistance in type II diabetes." (PMID 34554347, 2022). "Several randomised controlled clinical trials have shown that FGM may improve glucose control in patients with type 1 diabetes and those with type 2 diabetes on insulin therapy." (PMID 36251516, 2022). "Indeed, in the genesis of type 2 of diabetes, the existence of insulin sensitivity induces high blood levels of insulin and an increase in circulating levels of insulin-like growth factors (IGF)." (PMID 36277886, 2022). "This alteration in post-prandial microvascular response is probably related to microvascular insulin resistance which likely plays an important role in glucose disposal by controlling the rate of glucose and insulin delivery to myocytes and is involved in type 2 diabetes pathogenesis." (PMID 36550568, 2022). "However long-term treatment of patients with type 2 diabetes often still requires the introduction of exogenous insulin to provide the best control of plasma glucose levels, once the initial treatment paradigms have failed." (PMID 34863942, 2022). "Thus, a comprehensive assessment of the metabolic effects of melatonin treatment with direct measurements of insulin sensitivity and β‐cell function in patients with type 2 diabetes stratified on rs10830963 genotype is warranted." (PMID 35619221, 2022). "The enrichment results and grouping studies confirmed a close relationship between the TAC, pyruvate metabolism, and type II diabetes, indicating that cluster B may be resistant to insulin and glycometabolism disorder." (PMID 36468034, 2022). "In insulin resistant states, such as type 2 diabetes, LDL catabolism is decreased." (PMID 35439985, 2022).